AFP (alpha fetoprotein)
Diseases named in the same sentence as AFP in open-access papers (continued):
Sharing a sentence is not in itself a finding about the gene and the disease.
Cirrhosis (continued). "However, elevated serum AFP levels can also be observed in several other medical conditions, including acute and chronic hepatitis, cirrhosis, colitis, and germ cell tumors." (PMID 37174100, 2023). "To evaluate whether the combined effect of NPG on HBV‐HCC survival was modified by other variables, we performed stratified analysis by age, sex, smoking status, drinking status, cirrhosis, AFP, embolus, and BCLC stage." (PMID 38151984, 2023). "Additionally, further analysis demonstrated that AFP was also an independent factor for advanced fibrosis (p = 0.002) and cirrhosis (p = 0.010)." (PMID 37241155, 2023). "Notably, serum AFP exhibited the highest AUROC in diagnosing cirrhosis compared to significant fibrosis and advanced fibrosis." (PMID 37241155, 2023). "A review of the patients’ histories found that these 4 patients had hepatitis or cirrhosis, which may be responsible for the elevated AFP." (PMID 37578576, 2023). "Incidence rates of PLC were 48.4 versus 7.5 per 1000 person-years in those with and without thrombocytopenia, 71.6 versus 22.6 per 1000 person-years in those with AFP >10 ng/mL versus ≤10 ng/mL, and 73.7 versus 17.3 per 1000 person-years in those with Child-Pugh B versus A cirrhosis." (PMID 36881615, 2023). "The nomogram for predicting prognosis was developed based on the following 4 independent prognostic predictors: Differentiation (Well, Moderately, or Poorly/Undifferentiated), Tumor size (< 3 cm, 3–5 cm, 5–10 cm, or ≥ 10), AFP (Positive or Normal), and Fibrosis (Normal or Cirrhosis)." (PMID 36717904, 2023). "However, the specificity of AFP is low, as it can also be increased in flares of HBV/HCV infection, cirrhosis, or other underlying liver diseases." (PMID 37568696, 2023). "Australian national guidelines recommend biannual screening with ultrasound and consideration of AFP testing in people living with CHB who are at increased risk of HCC; this includes all patients with cirrhosis and Indigenous Australians who are older than 50 years." (PMID 37023060, 2023). "However, this subgroup was also distinct from S-MAFLD tumours due to being more likely to have cirrhosis, with smaller tumours and higher AFP level." (PMID 37470858, 2023). "Besides, in the younger patient group (age ≤65), patients in the RFA group were significantly older, had a higher level of AFP, and were less likely to be classified as having cirrhosis compared to those in the HR group." (PMID 36883222, 2023). "Moreover, serum AFP demonstrated superior diagnostic accuracy over APRI and FIB-4 in forecasting significant fibrosis, advanced fibrosis, and cirrhosis in HBeAg-positive CHB patients." (PMID 37241155, 2023). "In addition, the aetiology of liver disease, presence of cirrhosis, alpha-fetoprotein levels, tumour burden, and other factors affect the response to sorafenib." (PMID 36803349, 2023). "By analyzing the data of 116 cirrhotic HCC versus 158 patients with cirrhosis, we found that the median values for AFP, DCP (PIVKA-II), and AFP-L3 were significantly higher in patients with HCC than in those with cirrhosis, especially in HCC patients with BCLC stage B, C and D." (PMID 37708457, 2023). "The correlation between WDR45B expression level and clinical pathological characteristics including age, sex, T stage, macroscope vein invasion, microvascular invasion, cirrhosis, tumor involvement, and Alpha-fetoprotein (AFP) IHC staining was analyzed by chi-square test." (PMID 36900050, 2023). "The proportion of HBV infection and cirrhosis was 58 (96.7%) and 33 (55.0%) respectively, 27 patients (45.0%) had Microvascular invasion, 8 patients (13.3%) had Tumor thrombus and 40 patients (33.3%) with preoperative AFP ≥400 ng/ml." (PMID 35921289, 2022).
Cirrhosis (continued). "The model that incorporated clinical and radiological signatures such as serum AFP level, cirrhosis, PT, shape, hepatobiliary-phase peritumor hypointensty, and intra-tumoral hemorrhage had higher AUC values than the radiomics model, which corroborates the results of Xu’s research." (PMID 35392229, 2022). "AFP levels and the presence of histological features, including tumor differentiation, number and size of the tumors, microvascular invasion, capsule invasion, satellite nodules, hepatic steatosis, and cirrhosis, were similar among the three groups." (PMID 36366510, 2022). "As we have already mentioned, elevated AFP can also be explained by the existence of advanced chronic disease and it is true that the subjects who presented the higher AFP levels in our study also had decompensated cirrhosis." (PMID 35497085, 2022). "The American Association for the Study of Liver Disease (AASLD) recommended surveillance for HCC using ultrasonography with or without alpha-fetoprotein every 6 months in the high-risk individuals: only in cirrhosis and some non-cirrhosis hepatitis B carrier." (PMID 36203910, 2022). "Similar to the findings obtained from the entire cohort, subgroup analysis of patients with HCV-induced cirrhosis demonstrated that the combination of AFP + PIVKA-II performed the best (AUC 0.931 [0.888–0.961]) over any individual or combinations of biomarkers." (PMID 36079006, 2022). "In addition, serum AFP levels have been reported to be not only associated with HCC but also to be elevated in patients with benign liver diseases, such as hepatitis and cirrhosis." (PMID 36584078, 2022). "This study found that high preoperative serum AFP levels were associated with a worse prognosis regardless of the presence or absence of cirrhosis in patients with rHCC." (PMID 35342424, 2022). "The Guidelines published by the American and European Association for the Study of liver disease (AASLD and EASL) recommend in adults with cirrhosis a close surveillance with abdominal ultrasonography at intervals of 6 months and an optional alpha-fetoprotein (AFP) screening." (PMID 36551958, 2022). "As HBV-related hepatitis or cirrhosis may contribute to elevation of AFP, further validation is needed." (PMID 35251977, 2022). "However, haemoglobin, platelet count, serum albumin and alpha-fetoprotein (AFP) levels were significantly higher in the HCC patients than the cirrhosis patients." (PMID 36099308, 2022). "Significant differences were observed in preoperative AFP level (p<0.001), presence of cirrhosis (p=0.025), tumor number (p<0.001), satellite lesions (p<0.001), maximal diameter (p<0.001), histological grade (p<0.001) and presence of MVI (p<0.001) and PVTT (p<0.001)." (PMID 36203429, 2022). "High AFP might be expressed in patients with aggravation of chronic hepatitis, cirrhosis, or cholangiocarcinoma (low specificity)." (PMID 35547447, 2022). "The RIs correlated well with AFP, cirrhosis stage, and CYP2E1 activity." (PMID 35314790, 2022). "Meanwhile, the HCC group had a higher AFP value than the hepatic cirrhosis group (p = 0.012)." (PMID 36211468, 2022). "The clinicopathological analyses were performed for FGFR1, FGFR2, FGFR3 and FGFR4 against age, sex, grade stages, tumor stages, HCV, AFP, cirrhosis, vascular invasion, and cell type (atypical, dysplastic/polygonal, neoplastic) using different statistical approaches." (PMID 35683481, 2022). "In patients with cirrhosis or chronic hepatitis exacerbation higher AFP levels may be observed (low specificity)." (PMID 35996514, 2022). "In addition, combination of GPC-3 + AFP and GPC-3 + GP73 got great diagnostic value in HCC versus cirrhosis groups; the combination of GPC-3 can also improve the diagnostic accuracy of biomarkers." (PMID 36212469, 2022). "Second, in addition to tumor response, changes in AFP may also be affected by cirrhosis or chronic viral hepatitis." (PMID 36686731, 2022).
Cirrhosis (continued). "The TARE and Combo groups had similar baseline characteristics in age, gender, Child-Pugh score, MELD score, AFP value, etiology of liver disease, tumor distribution, percentage of patients with cirrhosis, portal vein tumor thrombus (PVTT), and extrahepatic metastases." (PMID 35518553, 2022). "However, AFP > 400, intraoperative blood loss, and tumor diameter > 5 cm were independent risk factors for HCC with cirrhosis only." (PMID 35313836, 2022). "Moreover, it was more reliable than serum AFP level, tumor vascular invasion, cirrhosis and TNM stage for OS prediction." (PMID 35193591, 2022). "They concluded that elevated serum AFP levels above 7 ng/mL significantly predicted the development of HCC within one year in these patients but found that 69% of patients with cirrhosis who eventually developed HCC had serum AFP less than or equal to 7 ng/mL when they were diagnosed with HCC." (PMID 36421714, 2022). "Nevertheless, the PR risk score was not correlated with tumor size, history of cirrhosis, clinical stage, and serum levels of AFP and ALT." (PMID 35368686, 2022). "Surveillance using abdominal ultrasound with or without serum alpha-fetoprotein (AFP) levels every six months is recommended by current guidelines for patients with cirrhosis and has been associated with improved survival." (PMID 36533190, 2022). "Nonetheless, we have conceded that sphingolipid family members discriminate between HCC and cirrhosis, and might represent excellent biomarkers far better than AFP." (PMID 35268381, 2022). "After constructing the HCC predictive model for the five‐gene signature for the high‐ and low‐risk groups, we created a table for clinical information patients in GSE14520 dataset, including gender, age, ALT, tumor size, multinodular, cirrhosis, serum AFP, and TNM stage." (PMID 33934539, 2021). "Therefore, we evaluated different glycopeptides as complement of AFP and different groups of glycopeptides that showed common changes between the cirrhosis and HCC samples." (PMID 34436504, 2021). "However, AFP is also increased in many other diseases such as liver cancer, cirrhosis, lymphoma, bone fracture and Wilms’ tumor, suggesting reduced specificity." (PMID 34422636, 2021). "Notably, clinical T stage, presence of cirrhosis, age, alpha-fetoprotein levels, and haemoglobin levels are independent prognostic factors for survival." (PMID 34126955, 2021). "Consistent with other reports, a specificity around 95.12%–96.3% revealed the superior discriminating power of PIVKA‐II under the context of CHB and cirrhosis than AFP, supporting the opinion that PIVKA‐II is more specific for HCC surveillance in HBV‐related high‐risk patients." (PMID 34590755, 2021). "Furthermore, portal hypertension, AFP > 400 ng/mL, tumor size > 5 cm, moderate/severe cirrhosis, microvascular invasion, and moderate/poor tumor differentiation were identified as independent adverse prognostic factors for OS." (PMID 34381132, 2021). "In addition, the majority of patients had positive AFP (70%) and severe fibrosis and cirrhosis (77%)." (PMID 34887446, 2021). "Besides, more patients had AJCC II or III stage, well-differentiated tumors, positive AFP, severe fibrosis and cirrhosis and tumor size between 3.5 and 7.2 cm in the chemotherapy group." (PMID 34887446, 2021). "However, many studies have shown that several independent risk factors, including age, race, alpha-fetoprotein (AFP) status, cirrhosis, and treatment strategies, affect the survival and prognosis of patients with CHC." (PMID 34336671, 2021). "Although risk factors for recurrence, including tumor size, alpha fetoprotein (AFP), tumor differentiation, cirrhosis, surgical margin, serum HBV viral load, and metabolic syndrome, have been proposed to be associated with the prognosis of HCC, their clinical application is limited." (PMID 33718159, 2021).
Cirrhosis (continued). "No clinical factors, including age, sex, HBsAg status, microvascular invasion, tumor size, cirrhosis status, histological grade, AFP level, tumor encapsulation status and early recurrence status, were significantly associated with the upregulation of ZEB1 expression in HCC." (PMID 34234851, 2021). "In addition, only a minority of patients with high TBS/high AFP had underlying cirrhosis (7.7%), while a significantly higher proportion (43.8%) of patients with low–medium TBS/low AFP had a cirrhotic liver." (PMID 33670174, 2021). "Moreover, alpha-fetoprotein (AFP) levels were significantly higher in HCC patients than those with cirrhosis and chronic hepatitis (p < 0.01 for both)." (PMID 34451956, 2021). "Furthermore, portal hypertension, Child–Pugh grade B liver function, AFP > 400 ng/mL, tumor size > 5 cm, intraoperative blood transfusion, moderate/severe cirrhosis, microvascular invasion, and moderate/poor tumor differentiation were associated with worse OS." (PMID 34381132, 2021). "In addition to Chibby, serum AFP (≥200 ng/mL; p = 0.002), cirrhosis (p < 0.001), vascular invasion (p < 0.001), advanced TNM stage (p < 0.001), and advanced histological grade (p < 0.001) were associated with poorer OS after resection in patients with HCC." (PMID 34199695, 2021). "However, approximately 30%–40% of LIHC patients are AFP-negative, and about 20%–50% of patients with chronic hepatitis or cirrhosis are AFP-positive." (PMID 34488769, 2021). "Furthermore, significant differences were observed between cHCC-CC and CC groups in terms of diabetes mellitus, alcohol use, cirrhosis, AFP level ≥ 200 ng/mL, operative margin > 1 cm, major hepatectomy, microvascular invasion, and macrovascular invasion." (PMID 33413162, 2021). "An important aspect is that in patients with AFP levels below 200 ng/mL, the diagnostic efficiency was good because the use of circSMARCA5 achieved an AUC of 0.847 in discriminating HCC vs. Hepatitis patients and an AUC of 0.706 in the HCC vs. Cirrhosis group." (PMID 34944400, 2021). "In the PSM matched cohort, the effects of pre-operative AVT on prognosis were further assessed and compared when the participants were stratified by several key clinicopathological factors, including HBV-DNA load, HBeAg, EGV, AFP, tumor size, cirrhosis and MVI." (PMID 33391413, 2021). "However, a meta-analysis on HCC surveillance has demonstrated that ultrasound alone is less sensitive than ultrasound associated with AFP (sensitivity of 45% versus 63%, relative risk of 0.81 for early-stage HCC in patients with cirrhosis)." (PMID 33918270, 2021). "In addition to the CNLC staging system, the two nomograms integrated three independent risk factors for OS, including cirrhosis, GGT and tumor differentiation, and integrated AFP for predicting RFS." (PMID 35127471, 2021). "However, AFP alone is not subjected to liver cancer detection guidelines, as a high amount of AFP is also detected in the serum of patients with cirrhosis, HBV, and HCV." (PMID 34440168, 2021). "Furthermore, we also built multivariable Cox models using TNM stage, BCLC stage, cirrhosis, and AFP as co-factors." (PMID 34094907, 2021). "Indeed, fucosylated alpha‐fetoprotein is an established disease marker for HCC in the setting of cirrhosis." (PMID 32557671, 2020). "In addition, AFP, tumor size, tumor number, cirrhosis, HBsAg, microvascular invasion, BCLC stage, and TNM stage were all significantly associated with OS." (PMID 32955798, 2020). "In addition, increased AFP levels can be found in the setting of cirrhosis patients with active hepatitis, elevated serum alanine aminotransferase (ALT), or non-HCC malignancies." (PMID 33297335, 2020). "Our results indicated that WFA+-M2BP could be a satisfactory biomarker for staging cirrhosis, and its combined use with AFP may further improve its predictive accuracy for HCC." (PMID 32601332, 2020).
Cirrhosis (continued). "However, there was no statistical significance between SNORA71A expression with other clinicopathologic characteristics, such as hepatitis B, AFP, or cirrhosis." (PMID 33062075, 2020). "The study specifically analyzed the value of the serum AFP level in patients with chronic hepatitis B and cirrhosis according to different ALT levels, illustrating ALT > 2 ULN might significantly affect AFP." (PMID 33490235, 2020). "In addition, stratified survival analysis indicated that the MSH still exhibited good prognostic value in different subgroups classified by AFP, cirrhosis, Child-Pugh A, tumor histologic grade, and AJCC stage." (PMID 31998802, 2020). "AFP performed well in distinguishing HCC from cirrhosis, thus ensuring the test is made affordable for patients could potentially increase HCC surveillance among at-risk patients in Ghana." (PMID 33357229, 2020). "Furthermore, miR-205 showed improved detection specificity and sensitivity compared to the Alpha fetoprotein (AFP) in liver cancer patients versus cirrhosis versus normal controls." (PMID 32854238, 2020). "Moreover, stratified analysis also indicated good prognostic value in different subgroups classified by AFP, cirrhosis, Child-Pugh A, tumor histologic grade, and AJCC stage, which, to some extent, suggested the greater reliability and general utility of MSH." (PMID 31998802, 2020). "Elderliness, male, elevated ALT, AST, NLR, AFP, cirrhosis, HBeAg+, and no‐antiviral treatment were independent risk factors for HBV‐HCC." (PMID 32150664, 2020). "Certain factors may determine AFP growth, among which cirrhosis, high MELD (Model for End-stage Liver Disease) scores, and high ALT (Alanine Aminotransferase)." (PMID 32341704, 2020). "Recently, Loglio and colleagues investigated the performance of PIVKA-II alone or in combination with AFP in 212 nucleos(t)ide analogues-treated patients with HBV-related cirrhosis (64 HCC and 148 HCC-free controls) for the early detection of HCC during surveillance." (PMID 33142893, 2020). "Initially, the clinical data from GEO database was insufficient and there was no additional valuable information concerning prognosis, including Child-Pugh scoring, cirrhosis scoring, AFP levels, tumor size and vascular invasion as well as therapeutic interventions." (PMID 32913470, 2020). "This important finding strongly supports the adoption of the AFP model as a selection tool for HCC patients in programs with HBV-related cirrhosis, which may be useful in Asian countries." (PMID 32974380, 2020). "Our results indicated that the MSH still exhibited good prognostic value in different subgroups classified by AFP, cirrhosis, Child-Pugh A, tumor histologic grade, and AJCC stage, which, to some extent, suggested the greater reliability and general utility of the MSH." (PMID 31998802, 2020). "For patients with cirrhosis, our analysis showed that AFP and vascular invasion, but not risk score, correlated significantly with RFS in univariate analysis." (PMID 32592379, 2020). "Compared with other clinical indicators (gender, age, ALT, cirrhosis, main tumor size, multinodular, BCLC stage, TNM stage, AFP, and risk score), the BCLC stage, TNM stage, and risk score showed better potential feasibility as independent prognostic factors for the RFS of HCC." (PMID 33163533, 2020). "Elderliness, male sex, elevated ALT, AST, NLR, AFP, cirrhosis, HBeAg+, and no‐antiviral treatment were independent risk factors for HBV‐HCC." (PMID 32150664, 2020). "Tumor size, cirrhosis, TNM stage, Barcelona Clinic Liver Cancer (BCLC) stage, and alpha-fetoprotein (AFP) levels were all significantly associated with survival in the GSE14520 cohort; tumor size could also predict survival in the LIRI-JP cohort." (PMID 31036064, 2019).